FOXC1 (forkhead box C1)
Diseases named in the same sentence as FOXC1 in open-access papers (continued):
Sharing a sentence is not in itself a finding about the gene and the disease.
tumor (continued). "FOXC1 expression has been studied in epithelial tumor cells of numerous malignancies, such as the breast, bladder, lung, uterus, liver, and the stomach, promoting fibrosis and epithelial‐to‐mesenchymal transition by regulating FGFR thereby influencing tumor development and progression." (PMID 39404228, 2024). "The miR-18a/low tumours had higher expression of the luminality-associated genes like ESR1, GATA3, FOXA1, XBP1 and TFF1 and a lower expression of the basality-associated genes such as KRT18, KRT17, FOXC1, ANLN, STIL and MIA (p < 0.05)." (PMID 38786043, 2024). "Furthermore, FOXC1 knockdown led to a notable reduction in the in vitro sphere-forming ability of tumor cells." (PMID 38413558, 2024). "Nevertheless, the knockdown of FOXC1 significantly mitigated these effects of IGF-1 on tumor cells." (PMID 38413558, 2024). "FOXC1, as a transcription factor, is involved in normal embryonic development, regulates the development and function of many organs, and plays a crucial role in tumour development and metastasis." (PMID 38429902, 2024). "While they analyzed FOXC1 expression by DNA microarray on tumor DLBCL cell lines, we analyzed FOXC1 protein expression on DLBCL‐associated dendritic cells, both studies demonstrated that FOXC1 expression was significantly correlated to two or more extranodal sites." (PMID 39404228, 2024). "Notably, while previous studies primarily focused on FOXC1 expression in tumor cells, our research emphasizes its expression in stromal cells, where FOXC1 was preferentially expressed compared with tumor cells." (PMID 39404228, 2024). "The number of FOXC1‐positive stromal cells and pERK1‐2‐positive tumor cells varied among cases." (PMID 39404228, 2024). "High expression of FOXC1 correlates with invasive tumor biological behaviors and poor prognosis." (PMID 38811720, 2024). "Despite these limitations, the observed improvement in prognostic accuracy with the inclusion of these markers highlights the promising potential of targeting FOXC1‐positive stromal cells and pERK1/2 tumor cells as innovative therapeutic strategies for treating recurrent and aggressive DLBCL." (PMID 39404228, 2024). "Notably, FOXC2 has the capacity to modulate the general upkeep of tumor cells and is involved in lipid alteration via kinases in tumor cells, whereas the role of FOXC1 in cancer metabolism is still a topic of research." (PMID 37626655, 2023). "Moreover, the expressions of TIMP1, PGF, FSTL3, SNAI1, and FOXC1 were significantly up‐regulated in the tumor tissues." (PMID 37017587, 2023). "However, how FOXC1 regulates immune response genes and influences the immunosuppressive tumor microenvironment is poorly understood." (PMID 38107056, 2023). "Besides, the presence of FOXC1 is characteristic of immuno-suppressed TNBC in a further subclassification of these tumours." (PMID 35267409, 2022). "It is known that FOXC1 expression is negatively controlled by a class of small non-coding RNA molecules, microRNA-133b, and that oxidative stress inhibits the expression of tumor-suppressor microRNAs, including microRNA-133b." (PMID 35365611, 2022). "Collectively, these findings present a unique opportunity for testing in cancer clinical trials where FOXC1 expression status may be found to be useful in predicting efficacy of Perfenidone in ameliorating tumor growth and/or metastatic dissemination." (PMID 34540690, 2021). "Furthermore, the results showed that FOXC1 can promote growth of GC by modulating the tumor cell cycle, as mediated by c-MYC and cyclin D1, further supporting the role of FOXC1 in GC progression." (PMID 33987183, 2021). "FOXC1 plays an important role in organ development and tumor growth, but its role in GC tumor growth remains unknown." (PMID 33987183, 2021). "Phenotypically, overexpression of FOXC1 results in increased tumor growth and migration." (PMID 33854062, 2021).
tumor (continued). "Furthermore, deletion of e1 or e2 led to a significant reduction of clonogenic formation ability, spheroid size, and tumor growth, indicating the functional importance of FOXC1 SE in TNBC tumorigenicity." (PMID 33854062, 2021). "There was a tendency of higher FOXC1 IHC score (defined as the number of positive tumor cells divided by the total number of tumor cells on the pathological section of FOXC1 IHC staining, Supplementary Methods) in SD plus PD patients compared with CR plus PR patients in arm E (P = 0.26)." (PMID 32719455, 2021). "However, although FOXC1 overexpression often drives aggressive traits in a wide array of human carcinomas, the mechanisms of FOXC1 deregulation that influence the oncogenic and metastagenic processes seem specific to each tumor setting." (PMID 34540690, 2021). "Moreover, we found that FOXC1 expression was notably upregulated in OSCC tissues compared with neighbor non-tumor tissues." (PMID 33968763, 2021). "Moreover, previous studies have indicated that FOXC1 promotes tumor proliferation through the PI3K-AKT, NF-KB and Wnt signaling pathways." (PMID 33987183, 2021). "Furthermore, a novel protein (circMAPK14‐175aa), encoded by circMAPK14, exhibited tumour‐suppressive effects and competed with upstream kinase MKK6 to facilitate ubiquitin‐mediated degradation of FOXC1 and block CRC development." (PMID 34709743, 2021). "Besides, miR-141 inhibition or overexpressed FOXC1 was shown to counterweigh the anti-tumor effects of LINC00242 knockdown in GC." (PMID 32587479, 2020). "Moreover, the tumor suppressor locus Ink4a/Arf, E-cadherin, FOXC1, and components of DNA damage repair pathways, which can be silenced by EZH2, have been shown to contribute to oncogenesis." (PMID 33163485, 2020). "To summarize, a consistent set of studies suggests that FOXC1 may play significant roles in overcoming the deleterious effects of hypoxia to sustain tumor progression." (PMID 30764547, 2019). "However, although overexpression of FOXC1 is frequent, the mechanisms of FOXC1 deregulation and how these influence oncogenic processes seem specific to each tumor setting." (PMID 30764547, 2019). "The elevated miR-138-5p expression induced by DHA treatment could decrease FOXC1 expression in tumor allografts." (PMID 31783879, 2019). "Meanwhile, overexpression of FOXC1 accelerated the tumor growth of MIA PaCa-2 xenografts." (PMID 29976975, 2018). "Immunoblot data confirmed the reduced expression of FOXC1 in xenograft tumor tissues." (PMID 29976975, 2018). "Accumulating evidence indicates that FOXC1 is involved in tumor development and metastasis." (PMID 30564302, 2018). "FOXC1 silencing resulted in significant reduction of the tumor growth of HPAC xenografts." (PMID 29976975, 2018). "Most of the studies chosen in our meta-analysis suggested that FOXC1 expression and cancer were associated, but none of them reported the relative risk between tumor stage and FOXC1 levels." (PMID 30564302, 2018). "IHC analysis confirmed the reduced levels of Ki67, Gli1, and VEGFR2 in FOXC1-silenced xenograft tumors, whereas FOXC1 overexpression upregulated these proliferative and metastatic markers compared with the xenograft tumors from empty vector control tumor group." (PMID 29976975, 2018). "FOXC1 is strongly expressed in the skeletal muscle, kidney, liver, and heart and plays important roles in embryogenesis, tissue-specific gene expression, and tumor development." (PMID 28695001, 2017). "The FOXC1 gene encodes a member of the forkhead box (FOX) family of transcription factors that are responsible for wide range of important roles such as embryogenesis, tissue-specific gene expression, and tumor development." (PMID 27463523, 2016).
tumor (continued). "Because transcriptional factors normally do not act alone, it is likely that FOXC1 is a component of a larger complex that regulates the initiation of transcription, and it is important to find the molecules that interact with FOXC1 to impact tumorigenesis and tumor progression." (PMID 24889262, 2014). "Methylation at the ABCB1 or GSTP1 promoter improved overall survival probably due to prolonged availability and activity of the drug in the cell while FOXC1 methylation might be a protective factor against tumour invasiveness." (PMID 20338046, 2010). "This might indicate that histone modifications or other mechanisms in addition to promoter hypermethylation silence FOXC1 in the unmethylated tumours." (PMID 20056007, 2010). "Therefore, we found that knocking down USP10 expression could mediate anti-tumor effects, which were partially blocked by FOXC1." (PMID 39430239, 2024). "Thus, we investigated TFs and their relationship to DEGs in these tumours, including FOXC1." (PMID 32093341, 2020). "Thus, it is conceivable that DNA methylation, H3K27 methylation, or potentially other mechanisms of silencing FOXC1 may be adopted during tumour evolution in a subtype-specific manner." (PMID 29959321, 2018). "This may suggest a possible role for the FOXC1/FOXCUT gene pair in tumor angiogenesis in OSCC." (PMID 24889262, 2014). "In triple-negative breast cancer (TNBC), LINC01123 is transcriptionally amplified by FOXC1, which directly binds to the LINC01123 promoter and promotes malignant cellular processes in tumor cells." (PMID 40255398, 2025). "According to the UALCAN database, the expression levels of PVT1, hsa-miR-143–3p, CDK1, FOXC1, YY1, and GATA2 show statistically significant differences between primary tumor samples and normal samples in the TCGA-LUAD dataset." (PMID 41080754, 2025). "In this research, we found that MN could facilitate the binding of OGT-570aa to FOXC1, thus reducing the biogenesis of alanine and asparagine, inducing ferroptosis, and inhibiting tumorigenesis and aggressiveness, which indicates its potential application as an inhibitor of tumor progression." (PMID 40416363, 2025). "Specifically, we enhanced the NCCN‐IPI with combinations of stromal FOXC1 and tumor pERK1‐2 as well as cell of origin, MYC/BCL2 double expression, and tumor pERK1‐2." (PMID 39404228, 2024). "Our results indicate potential interactions between tumor cells and microenvironment stromal cells of DLBCL, mediated by FOXC1." (PMID 39404228, 2024). "Employing traditional statistical methods and ML techniques, we provide an in‐depth analysis of the prognostic value of FOXC1 expression in stromal cells and pERK1‐2 expression in DLBCL tumor cells with established clinicopathological factors." (PMID 39404228, 2024). "The consistent results across both analytical methods, particularly for the highlighted combinations, reinforce the significance of stromal FOXC1 and tumor pERK1‐2 as crucial prognostic indicators within the DLBCL tumor microenvironment." (PMID 39404228, 2024). "FOXC1 knockdown engenders a decelerated growth rate within the FOXC1 knockdown group, evident from the CCK8 assay, and corroborated by tumor size and weight differentials in the in vivo comparison with the control group." (PMID 38413558, 2024). "The relationship between FOXC1 and L1CAM in TNBC was examined by investigating their protein expression levels using IHC in tumor samples from 40 TNBC patients." (PMID 38183514, 2024). "Several of the uniquely upregulated genes are previously shown to be involved in tumor cell proliferation such as UBE2C, GABRP, and FOXC1." (PMID 39198859, 2024).
tumor (continued). "During cancer progression and metastasis, FOXC1 mediates the cellular plasticity, partial EMT, treatment resistance, invasion, and migration of tumor stem cells." (PMID 39430239, 2024). "We observed that TrkB-mediated upregulation of DJ-1 stability activates tumor progression to malignancy by inducing an EMT program via upregulation of EMT-TFs, including Foxc1 and Foxc2, Snail, Goosecoid, Twist-1, and Twist-2." (PMID 37749450, 2023). "Beware of the inhibitory effect of Trichostatin A (TSA) on FOXC1 and FOXK2 expression; despite the present study confirming its tumor suppressor effect on TNBC cells, more research is needed to prove its actual roles in TNBC patients." (PMID 36292640, 2022). "Another tumour-promoting lncRNA, LINC01929, accelerates the tumour progression by targeting the miR-137-3p/FOXC1 axis in OSCC, suggesting a novel target for OSCC therapy." (PMID 36428681, 2022). "FOXC1 downstream targets, such as MYC, LINC01123, and MMP10, have been reported to regulate tumor progression in various cancer types." (PMID 35406487, 2022). "For instance, the expression level of FOXC1 was significantly increased in HCC and it functioned as an independent predictor for HCC survival and tumor recurrence." (PMID 35255005, 2022). "Cui and coworkers reported that FOXC1-overexpressed MDA-MB-231 cells, when injected orthotopically into the mammary glands of BALB/c nude mice, resulted in a marked increase in tumor formation efficiency compared to the control group." (PMID 34540690, 2021). "Previous reports showed that EZH2 targets a cascade of tumour suppressors, such as CDX1, FOXC1, LATS2, CDH1 and DAB2IP." (PMID 33336896, 2021). "Up-regulation of CTH significantly inhibited tumor growth induced by Huh7-FOXC1 cells, whereas down-regulated CTH rescued the decreased tumor growth mediated by FOXC1 knockdown by In vivo tumorigenicity assays." (PMID 33522955, 2021). "MiR-582-5p has tumor-suppressive functions and reduces the tumor cell proliferation and migration via targeting CDK1, FOXC1, and RAB27a." (PMID 33183321, 2020). "FOXC1 upstream transcript (FOXCUT) is alncRNA that is overexpressed in OSCC and promotes tumor cell proliferation and migration by regulating FOXC1 expression." (PMID 31336999, 2019). "Real-time PCR analysis of FOXC1 expression from 25 DCIS, 23 IDCs and 28 normal tissue samples showed lower gene expression levels of FOXC1 in both methylated and unmethylated tumours compared to normal tissue (P < 0.001)." (PMID 20056007, 2010). "The eight genes displaying variable DNA methylation patterns in a significant number of tumours (ABCB1, BRCA1, CDKN2A, FOXC1, GSTP1, IGF2, PPP2R2B and PTEN) within the discovery cohort were tested for association with survival by a logrank test." (PMID 20338046, 2010). "For FOXC1 significant differences in methylation levels were observed between normal breast tissue and IDC (P < 0.001) and mixed tumours (P < 0.001)." (PMID 20056007, 2010). "The downregulation of FOXC1, FOXC2, and SOX11 suggests these transcription factors may play a role in maintaining tumour differentiation and regulating metastatic behaviour, warranting further investigation." (PMID 40683913, 2025). "Moreover, transcription factor activity inference revealed the subcluster-specific expression of regulators such as FOXC1 and E2F1, highlighting the central role of transcriptional regulatory networks in shaping tumor phenotypes." (PMID 40496864, 2025). "CCK8 assays revealed that CBX7 and IGF-1R overexpression significantly increased tumor cell proliferation, counteracting the negative impact of FOXC1 knockdown." (PMID 38413558, 2024). "Taken together, we hypothesize that FOXC1 expression, primarily originating from stromal cells within the DLBCL tumor microenvironment, contributes to the aggressive biological behavior of DLBCLs." (PMID 39404228, 2024).
tumor (continued). "FOXC1 activates genes heralding EMT and tumor migration, it is a positive regulator of cancer stem cell function, and appears to be a downstream target of HIF1α-signaling, i.e., the FOXC1 expression enhances the adaptation to tumor hypoxia." (PMID 34659373, 2021). "Additionally, studies support that the interactions between FOXC1, the Notch signals, and VEGF control the expression of vascular genes and facilitate tumor angiogenesis in multiple steps." (PMID 32199127, 2020). "Since FOXC1 is highly expressed in many cancers and contributes to cancer cell growth and invasion, we also looked into FOXC1 expression in LUSC and LUAD cancer specimens with different tumor extents and lymphatic metastasis in TCGA mRNA expression database." (PMID 31783879, 2019). "The protein expression of FOXC1 was evaluated following OXA in LoVo and OR-LoVo tumor tissue." (PMID 31623173, 2019). "Seventeen of the 22 multivariant studies were excluded either because they did not investigate the relationship between FOXC1 expression and cancer, did not categorize their results by tumor stage, or did not evaluate FOXC1 expression immunohistochemically." (PMID 30564302, 2018). "Consistent with the notion that Foxc1 was a target of transcriptional silencing by Ezh2, immunofluorescence revealed that Ezh2 and Foxc1 did not co-localize in endpoint Tet-ON PyVmT tumours." (PMID 29959321, 2018). "Data also showed that there was higher FOXC1 expression in ERα‐negative tumor than that in ERα‐positive tumor." (PMID 28028927, 2017). "In an investigation of HOTAIR, forkhead box C1 (FOXC1), and miR-1, levels of HOTAIR and FOXC1 were increased, while levels of miR-1 were decreased in HCC tissues and HepG2 cells compared to normal liver cells and adjacent non-tumor tissues." (PMID 30159431, 2017). "In vivo, we also examined the negative relationship between miR-495 and FOXC1 and the opposite effects of tumour growth." (PMID 26198045, 2016). "In conclusion, FOXC1 may be co-amplified with FOXCUT in OSCC, and both of them may be functionally involved in the tumor progression of OSCC." (PMID 24889262, 2014). "We found that 19 of the 23 OSCC patients (82.6 %, p < 0.05) showed remarkably higher expression of FOXC1 mRNA in tumor tissues than in noncancerous tissues." (PMID 24889262, 2014). "The weak correlation between expression and DNA methylation for FOXC1 was due to the fact that the gene was already silenced in most tumours independent of its methylation status." (PMID 20338046, 2010). "The chromosomal region 6p25 harbouring the FOXC1 gene is frequently gained in ER negative tumours in line with our observation of low DNA methylation and high expression in basal and normal-like tumours." (PMID 20056007, 2010). "TGF-β1 could regulate the chemoresistance of tumor cells through complex mechanisms, such as inducing epithelial-mesenchymal transition, increasing the expression of MDR-related genes, and activating Smad2/3 and FOXC1 pathways." (PMID 36641471, 2023). "By virtue of being a transcription factor, and being a central hub gene controlling a network of hundreds of genes, it is not surprising that upregulation of FOXC1 in cancer does cast wide influence on a number of biologic processes critical for tumor survival and propagation." (PMID 34540690, 2021). "Taken together, these data suggested that FOXC1 plays a tumour suppressive role in non-BLBC subtypes and we hypothesized that the previously identified FOXC1 targets might facilitate this anti-metastatic program." (PMID 29959321, 2018).